MED27 (mediator complex subunit 27)
Description:
Component of the Mediator complex, a coactivator involved in the regulated transcription of nearly all RNA polymerase II-dependent genes. Mediator functions as a bridge to convey information from gene-specific regulatory proteins to the basal RNA polymerase II transcription machinery. Mediator is recruited to promoters by direct interactions with regulatory proteins and serves as a scaffold for the assembly of a functional preinitiation complex with RNA polymerase II and the general transcription factors.
Synonyms: CRSP34; CRSP8; TRAP37; MED3; CRAP34; NEDSCAC
Tractability: Small molecule: a structure with a bound ligand is known. PROTAC: ubiquitination databases record sites on it; its protein half-life has been measured.
Gene: Protein-coding gene on chromosome 9 (131,852,928 to 132,079,875, reverse strand). Ensembl gene ENSG00000160563.
Subcellular location: Nucleus
Subcellular location (Human Protein Atlas): Nucleoli; Nucleoplasm; Cytosol
Pathways (Reactome):
Gene expression (Transcription): Generic Transcription Pathway; MLL4 and MLL3 complexes regulate expression of PPARG target genes in adipogenesis and hepatic steatosis
Developmental Biology: Transcriptional regulation of white adipocyte differentiation
Disease: RSV-host interactions
Metabolism: PPARA activates gene expression
Gene Ontology:
Molecular function: protein binding; transcription coactivator activity
Biological process: regulation of transcription by RNA polymerase II; positive regulation of transcription elongation by RNA polymerase II; positive regulation of transcription initiation by RNA polymerase II; RNA polymerase II preinitiation complex assembly; transcription initiation at RNA polymerase II promoter
Cellular component: core mediator complex; nucleolus; nucleoplasm; nucleus; transcription regulator complex; mediator complex
Genetic constraint (gnomAD): Loss-of-function variants: 22 observed, 29.04 expected, observed/expected ratio (o/e) 0.76, 90% interval 0.54 to 1.08. The upper end of that interval is the gene's LOEUF score, 1.08, which puts it in group 4 of 6, group 1 being the genes least tolerant of losing a copy. Missense variants: 247 observed, 333.51 expected, observed/expected ratio (o/e) 0.74, 90% interval 0.67 to 0.82. Synonymous variants: 111 observed, 137.22 expected, observed/expected ratio (o/e) 0.81, 90% interval 0.69 to 0.95.
Gene-disease validity (ClinGen):
ClinGen rates the evidence that MED27 causes each of these diseases.
neurodevelopmental disorder with spasticity, cataracts, and cerebellar hypoplasia (autosomal recessive): Definitive.
Homologues: Orthologues: chimpanzee MED27 (100% identical), macaque MED27 (99% identical), pig MED27 (99% identical), guinea pig MED27 (98% identical), mouse Med27 (98% identical), rabbit MED27 (97% identical), rat Med27 (89% identical), zebrafish med27 (88% identical), dog MED27 (85% identical), tropical clawed frog med27 (81% identical), Drosophila melanogaster MED27 (37% identical).
Diseases named in the same sentence as MED27 in open-access papers:
MED27 is named in the same sentence as 24 diseases in open-access papers, as found by Europe PMC text mining. Sharing a sentence is not in itself a finding about the gene and the disease. The quoted sentences say what the papers report.
melanoma (2 papers, 2022 to 2025). A malignant, usually aggressive tumor composed of atypical, neoplastic melanocytes. "In addition, MED27 has been reported to be associated with melanoma, and thus mutations in the MED27 gene may be associated with AMD." (PMID 35627256, 2022).
osteosarcoma (2 papers, 2021 to 2022). A usually aggressive malignant bone-forming mesenchymal neoplasm, predominantly affecting adolescents and young adults. "In osteosarcoma cells, MED27 is a direct target of miR-18a, since it can bind to MED27 mRNA, and the expression of this miRNA suppresses tumor growth in mice." (PMID 35205279, 2022).
pituitary tumor (1 paper, 2025). A benign or malignant neoplasm affecting the pituitary gland. "In the pituitary tumor cohort (GSE169498), we identified a total of five MRGs (MED27, RARRES2, AKAP8L, RAB5B, and STK39) that are associated with the invasiveness of pituitary tumors." (PMID 40873641, 2025).
prostate carcinoma (1 paper, 2025). A carcinoma that arises from epithelial cells of the prostate gland. "The plot was thickened with associations between the expression of NCOA1, NCOA3, and MED27, lymph node involvement, and the overexpression of several genes linked to advanced prostate cancer stages." (PMID 40900470, 2025). "■ NCOA1, NCOA3, MED27, and ESRRA are associated with advanced prostate cancer." (PMID 40900470, 2025).
retinal disease (1 paper, 2014). "BBS9, MPP7, MED27, these three genes found here to interact with CFH have also been reported to be important for retinal disease." (PMID 24901472, 2014).
tumor (4 papers, 2014 to 2025). "MED27 has been found that is highly expressed in BC tissues and cells and its expression correlates with tumor size and grade and the high expression of MED27 had a poor prognosis." (PMID 35205279, 2022).
infection (1 paper, 2020). The state of being infected such as from the introduction of a foreign agent such as serum, vaccine, antigenic substance or organism. "Unexpectedly, distinct subunits appear to be involved in the response to this type of infection, in which the pathogen breaks through the cuticle, namely Med27 and possibly Med7 and Med29." (PMID 33746938, 2020).
MED27 also shares sentences with these, for which no sentence is quoted: cancer (3 papers); neurodevelopmental disorder (3); Cerebellar atrophy (2); developmental delay (2); microcephaly (2); thyroid cancer (2); anaplastic thyroid cancer (1); breast carcinoma (1); Cerebral atrophy (1); complex neurodevelopmental disorder (1); disseminated candidiasis (1); hematological cancers (1); hepatocellular carcinoma (1); Intellectual disability (1); liver cancer (1); movement disorder (1); neurological disorders (1).